FASN (fatty acid synthase)
Diseases named in the same sentence as FASN in open-access papers (continued):
Sharing a sentence is not in itself a finding about the gene and the disease.
prostate carcinoma (continued). "The treatment of prostate cancer cells with SFN (5 and 10 μM) resulted in the downregulation of acetyl-CoA carboxylase 1 (ACC1) and fatty acid synthase (FASN), inhibiting fatty acid synthesis." (PMID 36768284, 2023). "Two other miRNAs, miRNA-185 and miRNA-342, can block SREBP-1/2 and its downregulated targets, FASN and hydroxy-3-methylglutaryl CoA reductase (HMGCR), to inhibit prostate cancer tumorigenicity." (PMID 35912181, 2022). "Overexpression of fatty acid synthase (FASN) has been reported in breast, colon, ovarian, and prostate cancer." (PMID 35178126, 2022). "SREBP-1 and its downstream effectors, FASN and ACC, are upregulated in a TCGA cohort of prostate cancer and late-stage transgenic adenocarcinoma of mouse prostate tumor." (PMID 35912181, 2022). "Similar to prostate cancer, HCC has been shown to overexpress types of lipogenic enzymes, including acetyl-CoA carboxylase (ACC), ATP citrate lyase (ACL), and fatty acid synthase (FASN)." (PMID 35742944, 2022). "For example, visfatin upregulates fatty acid synthase (FASN), a key enzyme in de novo fatty acid biosynthesis pathway, through Akt- and ERK-dependent mechanisms to promote the growth of prostate cancer cells." (PMID 33535537, 2021). "FASN was dramatically increased in CRPC mouse tissues and prostate cancer patient tissues, as shown in the expression signature of prostate cancer patients." (PMID 34944692, 2021). "miR‐185 and 342 can inhibit SREBP‐1 and 2 expression and downregulate FASN and HMGCR that will, in turn, influence lipogenesis and cholesterogenesis in prostate cancer." (PMID 34766135, 2021). "Studies showed that SFN inhibited lipid synthesis by inhibiting key enzymes such as FASN and ACACA in prostate cancer." (PMID 34620841, 2021). "Lastly, miR-185 and miR-342 have been shown to control lipogenesis and cholesterogenesis by inhibiting SREBP-1 and -2 expression and downregulating their target genes (FASN and HMG-CoA reductase) in prostate cancer." (PMID 32577155, 2020). "Elevated fatty acid synthase (FASN) has been reported in both androgen-dependent and -independent prostate cancers." (PMID 31527721, 2019). "Lipidemic analysis on prostate cancer cells that had undergone EMT, showed increased triacylglycerols and fatty acid synthase (FASN)." (PMID 31849832, 2019). "The fatty acid synthase gene (FASN) was found to be a prognostic marker in breast and prostate cancer." (PMID 30889783, 2019). "The expression of the fatty acid synthase (FASN) enzyme and of the transcriptional regulator SREBP is significantly increased in prostate cancer and, particularly, in mCRPC." (PMID 31366128, 2019). "Exposure of prostate cancer cells to PEITC downregulate many fatty acid metabolism proteins, including acetyl-CoA carboxylase 1 (ACC1), fatty acid synthase (FASN) and carnitine palmitoyltransferase 1A (CPT1A)." (PMID 30445746, 2018). "In various cancers, including prostate cancer and ovarian carcinoma, upregulation of USP2 leads to an increase in the levels of deubiquitinated substrates such as fatty acid synthase, MDM2, cyclin D1 and Aurora-A." (PMID 29449607, 2018). "Several changes to key gene regulators of lipid metabolism, such as fatty acid synthase (FASN) and alpha-methylacyl-CoA racemase (α- AMACR) have been described in prostate cancer." (PMID 29156692, 2017). "For example, AICAR reduced expression of FASN and ACC resulting in inhibition of proliferation on prostate cancer cells." (PMID 29221189, 2017). "Inhibiting lipogenic enzymes such as fatty acid synthase (FASN), acetyl-CoA carboxylase (ACC), or ACLY produces anti-cancer effects both in prostate cancer cell lines and mouse models." (PMID 27248322, 2016). "In PC-3 and LNCaP human prostate carcinoma cells, hypoxia dysregulates the expressions of lactate dehydrogenase A (LDHA), fatty acid synthase (FASN) and mitochondrial aconitase (mACON) genes." (PMID 25476483, 2015).
prostate carcinoma (continued). "miR-342 can inhibit the expression of SREBP, resulting in down-regulation of FASN and 3-hydroxy-3-methylglutaryl CoA reductase (HMGCR) and inhibition of FA biosynthesis in prostate cancer cells." (PMID 26519053, 2015). "Identification of exosomal proteins using high performance LC-FTMS resulted in the discovery of PDCD6IP, FASN, XPO1 and ENO1 as new candidate biomarkers for prostate cancer." (PMID 24391718, 2013). "Both miR-185 and 342 inhibited the expression of SREBP-1 and SREBP-2 and their downstream genes, FASN and HMGCR, and further decreased the levels of fatty acid and cholesterol in prostate cancer cells." (PMID 23951060, 2013). "We analyzed 14 additional genes, including the AR-activated genes PSA, FKBP51, ORM1, STAG, Nkx3.1, FASN, AQP3, KLK2, and UGT2B; the AR-repressed genes DKK and FST; and the castration-resistant prostate cancer AR-regulated genes CDC20, CDK1, and UBE2C." (PMID 22761715, 2012). "Previous studies have shown that, in prostate cancer, caveolin-1 and KLF5/SREBP-1 function upstream of FASN." (PMID 20508725, 2010). "A number of genes including hepsin, myc, fatty acid synthase SPARC1 and EBNA-2 coactivator show similar expression patterns across multiple prostate cancer studies, and are also regulated in our study." (PMID 15892885, 2005). "In PC3 (prostate cancer) and A549 (lung cancer) cells, EGFR could be activated intracellularly via FASN-mediated protein palmitoylation, becoming a potential target for anticancer therapy." (PMID 39332525, 2024). "Nonetheless, a recent study indicates that FASN inhibition is highly detrimental to the growth of prostate carcinoma cell lines, while it does not affect the oncogenic properties of pancreatic adenocarcinoma cells." (PMID 39064589, 2024). "In addition, FASN enhances the production of membrane RTKs, including EGFR, ERBB2, and hepatocyte growth factor receptor/c-MET, in breast, ovarian, and prostate cancers, as well as non-Hodgkin lymphoma." (PMID 38933330, 2024). "Fatty acid synthase (FASN) catalyzes the synthesis of long-chain fatty acids from acetyl-CoA and malonyl-CoA and is highly expressed in most human cancers, such as breast, lung and prostate cancers." (PMID 38539242, 2024). "The compound also inhibited ribosomal 6 kinase (RSK) family proteins.BAY-3827 displayed excellent anti-proliferative effects against androgen-dependent prostate cancer cell lines by blocking HMGCR, fatty acid synthase (FASN) and PFKFB2, all of which are strongly up-regulated by androgen treatment." (PMID 36875093, 2023). "Prostate cancer is characterized by elevated de novo synthesis of fatty acid and overexpression of key fatty acid synthesis enzymes such as acetyl-CoA carboxylase (ACC) and fatty acid synthase (FASN)." (PMID 37108142, 2023). "As a consequence of the loss of the tumor suppressor gene PTEN, prostate cancer cells undergo metabolic reprogramming, resulting in fatty acid synthase (FAS) overexpression, the production of fatty acids and cholesterol, and the proliferation of prostate cancer cells that are malignant." (PMID 36824662, 2023). "The activation of the intrinsic pathway of apoptosis with camptothecin in the prostate cancer LNCaP cells stably overexpressing FASN did not induce cell death contrary to control LNCaP cells suggesting that FASN blocks the intrinsic pathway of apoptosis." (PMID 36934087, 2023). "The activity of the probes was determined against LNCaP cells, which highly express FASN, and PC3 prostate cancer cells, which express FASN at much lower levels and served as our negative controls." (PMID 35268652, 2022). "miRNA-21 overexpression increases cell proliferation and migration, as well as the levels of insulin receptor substrate 1 (IRS1), sterol regulatory element-binding protein 1 (SREBP-1), fatty acid synthase (FASN) and acetyl-CoA carboxylase (ACC) in human prostate cancer cells." (PMID 35457012, 2022).
prostate carcinoma (continued). "However, the effects of EMT on lipogenesis are controversial because there are other studies showing that in prostate cancer cells undergoing TNFα-induced EMT, FASN and lipogenesis are upregulated." (PMID 35054987, 2022). "Anti-cancer activity of quercetin such as induction of apoptosis, fatty acid synthase (FAS), inhibition of cell proliferation, reduction of metalloproteinase-2 (MMP-2), and metalloproteinase-9 (MMP-9) expression in prostate cancer cells were studied." (PMID 35971151, 2022). "Finally, FASN inhibition negatively regulates cytosolic phospholipase A2 (PLA2G4A) and estradiol 17‐beta‐dehydrogenase 12 (HSD17B12) in several prostate cancer cell lines." (PMID 33166087, 2021). "Fatty-acid synthase (FASN), which is involved in de novo FA synthesis, is also found to be overexpressed in numerous cancers, including breast, lung, stomach, ovary, colon, and prostate cancers." (PMID 34048454, 2021). "Finally, it has been described in prostate cancer that genetic alterations of ACACA, FASN, and SREBF1 predicted worse overall patient survival." (PMID 33194695, 2020). "Prostate cancer (PCa) is defined by dysregulated lipid signaling and is characterized by upregulation of lipid metabolism-related genes including fatty acid binding protein 5 (FABP5), fatty acid synthase (FASN), and monoacylglycerol lipase (MAGL)." (PMID 31831821, 2019). "A lipidomic approach performed on prostate cancer cells that underwent EMT following TNFα treatment revealed a significant increase in the synthesis of triacylglicerols (TAGs), sustained by a concomitant upregulation of fatty acid synthase (FASN)." (PMID 28352611, 2017). "Experimental studies suggest that FASN overexpression can mediate resistance to ADT in prostate cancer, although no clinical data are yet available." (PMID 28208703, 2017). "For instance, folate-targeted paclitaxel–fisetin nanoparticles downregulated ABCG2 and triggered apoptosis in resistant ovarian cells, whereas NanoOrl, an orlistat-loaded formulation, restored taxane sensitivity via fatty acid synthase inhibition, independent of P-gp in prostate cancer." (PMID 40806254, 2025). "However, although [11C]acetate uptake by prostate cancer cells correlates with FASN expression, no FASN-specific PET probes currently exist." (PMID 35268652, 2022). "In addition, FASN inactivation with siRNA in LNCaP cells reduces pseudopodia and invadopodia formation, cell adhesion, migration and invasion, and FASN inhibition negatively regulates PLA2G4A and HSD17B12 in several prostate cancer cell lines." (PMID 33166087, 2021). "The prostate cancer cell lines were able to take up fatty acids from the culture medium, and the availability of fatty acids affected sensitivity of these cells to C75 but not the other FASN inhibitors tested." (PMID 33083663, 2020). "Besides, expression of two key protein factors controlling de novo lipogenesis, SREBP-1 and FASN, was highly elevated in clinical prostate cancer and CRPC specimens compared to normal/non-tumor prostate tissues." (PMID 32276528, 2020). "Furthermore, suppression of the NF-κB activity via inhibition of FASN in both LNCaP and PC3 cells may provide a novel strategy for radiotherapy of the prostate cancer." (PMID 31527721, 2019). "However, suppression of FASN by RNAi in the human prostatic cancer cell line LNCaP reduces fatty acid synthesis without an alteration of cholesterol synthesis." (PMID 25255125, 2014). "Examples include fatty acid synthase (FASN), a metabolic oncogene, and 3-hydroxy-3-methylglutaryl CoA reductase (HMGCR), the rate-limiting step in cholesterol biosynthesis; both proteins have been reported to be involved in the development and progression of prostate cancer." (PMID 23951060, 2013).
prostate carcinoma (continued). "Therefore, FASN-targeted therapy would be an effective treatment for complementing hormone therapy against FASN-positive prostate cancers with aggressive features and [1-11C]acetate PET could be applied to select the patients who can undergo the FASN-targeted therapy." (PMID 23741342, 2013). "The selective FASN inhibitor IPI‐9119 reduced both cell migration and invasion in Pten+/− prostate cancer cells, but not their viability." (PMID 33166087, 2021). "This has been reported in prostate cancer cells, which could be inhibited only by C75 and SB204990, inhibitors of FASN and ACLY, respectively, in the absence of lipoprotein, the transporter of exogenous fatty acid and cholesterol." (PMID 30180878, 2018).
Hepatic steatosis (161 papers, 2011 to 2025). Steatosis is a term used to denote lipid accumulation within hepatocytes. "Our data showed that PFOS exposure caused hepatic steatosis, as evidenced by significant increases in triglyceride levels, expression of ATP-citrate lyase, and fatty acid synthase, as well as fasting insulin levels." (PMID 38075064, 2023). "Hepatic FASN deficiency in ob/ob mice ameliorates hepatic steatosis but exacerbates liver dysfunction." (PMID 37681411, 2023). "In ob/ob mice, hepatic FASN deficiency ameliorated hepatic steatosis and improved glucose tolerance to a greater extent than in Mc4r-KO mice, but it exacerbated fed hyperglycemia and liver dysfunction." (PMID 37681411, 2023). "Hepatic FASN deficiency was previously shown to exacerbate hepatic steatosis and liver dysfunction as well as to induce relative hypoglycemia and improve glucose tolerance in nonobese mice fed a ZFD but not in those fed a NCD." (PMID 37681411, 2023). "In leptin-deficient mice, FASN ablation alleviated hepatic steatosis and improved glucose tolerance but exacerbated fed hyperglycemia and liver dysfunction." (PMID 37681411, 2023). "In addition, hepatic FASN deficiency ameliorated hepatic steatosis to a lesser extent in Mc4r-KO mice than in ob/ob mice, as assessed on the basis of hepatic triglyceride content (70% versus 96% inhibition)." (PMID 37681411, 2023). "On the other hand, as observed in ob/ob mice, targeting of hepatic FASN in obese individuals may exacerbate hyperglycemia and liver dysfunction, despite an associated amelioration of hepatic steatosis and improvement in glucose tolerance." (PMID 37681411, 2023). "In this regard, it has been reported that FASN gene expression in liver may be associated with hepatic steatosis." (PMID 35681829, 2022). "It has been reported that hepatic steatosis and liver injury associated with steatohepatitis in mice can be alleviated by branched-chain amino acid diet supplementation, and by suppressing gene expression and the protein level of fatty acid synthase (FAS)." (PMID 33291840, 2020). "Interestingly, previous studies have demonstrated that treatment of FASN inhibitor in obese mice caused dramatic improvement of hepatic steatosis, which was consistent with our results." (PMID 28088781, 2017). "SREBP-1c knockdown in CONVR ZFD-fed mice reduced hepatic steatosis and suppressed fatty acid synthase expression." (PMID 40345386, 2025). "To further elucidate the mechanism underlying the effects of LG on DXM-induced fatty liver, we explored the role of AMP-activated protein kinase (AMPK) as a potential regulator of FASN and CD36 expression." (PMID 39820544, 2025). "To gain further insight into the underlying causes of hepatic steatosis induced by chronic HFD consumption, we investigated the expression profiles of major regulatory genes necessary for hepatic lipid metabolism (FASN, ACC1, SCD1, SREBP-1c, and CD36)." (PMID 40076869, 2025). "Our findings identified SNPs significantly associated with disease risk, demonstrated altered expression of immune (IL-6, IL-8), antioxidant (SOD3, HMOX1), and lipogenic (ACACA, FASN) genes, and confirmed hepatic steatosis via ultrasonography." (PMID 41012815, 2025). "For instance, GPR55‐deficient mice show defective insulin signaling and a significant increase in liver fatty acid synthase, leading to hepatic steatosis." (PMID 39417398, 2024). "In contrast, USP14 directly interacts with and stabilizes fatty acid synthase (FASN) to exacerbate liver steatosis, insulin resistance, and hyperglycemia." (PMID 39033101, 2024). "In the liver, DZF intervention resulted in a reduction in hepatic steatosis and lipid droplets, accompanied by a decrease fatty acid synthase (FASN) and stearoyl-CoA desaturase 1 (SCD1) and fatty acid transport protein 2 (FATP2)." (PMID 38327989, 2024).